ENSG00000241352 (ribosomal protein S6 (RPS6) pseudogene)
Synonyms: RPS6_9_1210; RPS6P1
Gene: Processed pseudogene on chromosome 12 (12,850,982 to 12,851,740, forward strand). Ensembl gene ENSG00000241352.
Diseases named in the same sentence as ENSG00000241352 in open-access papers:
ENSG00000241352 is named in the same sentence as 1 disease in open-access papers, as found by Europe PMC text mining. Sharing a sentence is not in itself a finding about the gene and the disease.
ENSG00000241352 shares sentences with these, for which no sentence is quoted: cancer (1 paper).